POLE (DNA polymerase epsilon, catalytic subunit)
Diseases named in the same sentence as POLE in open-access papers (continued):
Sharing a sentence is not in itself a finding about the gene and the disease.
cancer (continued). "Signature 10 features altered the activity of the error-prone polymerase POLE and is often found in six cancer types, including CRC." (PMID 33959500, 2021). "In silico analysis confirmed that POLE-mutant cancers are predicted to display more antigenic neoepitopes than other EC, providing a potential rational for POLE immunogenicity." (PMID 34199461, 2021). "There was a significant association among POLE expression with the ESTIMATE score, immune score, and stromal score of pan-cancer." (PMID 34950188, 2021). "A closer examination revealed higher mutation rates in the POLE subtype prevalent in young adult UCEC, suggesting cancer subtype and onset age need to be jointly considered in estimations of mutation rate in selected cancer types." (PMID 34788626, 2021). "Cox regression analyses were implemented to explore the effect of POLE expression on the prognosis of pan-cancer." (PMID 34950188, 2021). "Of the 33 cancer types in the TCGA database, we identified 15 cancer types (PANCAN) with 2 or more cases that possessed mutations in the POLE protein coding region." (PMID 32838755, 2020). "Next, we calculated an “MMR escape ratio” to quantify the relative amount of replication errors that escapes MMR repair in the POLE only mutant cancers compared with the POLE and MMR double mutants." (PMID 32170069, 2020). "This study furthers our understanding of the POLE mutagenic process in cancer and provide important insights into carcinogenesis in cancers with such mutations." (PMID 32012149, 2020). "Reassuringly, the POLE mutant cancer had 2% of MSI sites being unstable, meaning it was microsatellite stable (MSS), as is typical in POLE mutant cancer." (PMID 32306292, 2020). "The assessment of the functional impact of cancer-associated DNA polymerase δ and ε variants (POLD1 and POLE) has been evaluated in yeast by constructing strains carrying the correspondent mutated amino acid identified by aligning yeast and human sequences." (PMID 32656256, 2020). "The significant correlation between POLE and TILs suggests that POLE is involved in DNA proofreading/repair as well as recruitment of immune cells to mediate cancer surveillance." (PMID 32433714, 2020). "Unexpectedly, our results showed that POLE expression were higher in primary cancer than in healthy tissue." (PMID 32433714, 2020). "Previous studies have shown that POLE proofreading-mutant cancers are a molecularly distinct group of tumors with a striking mutation burden and distinctive mutation signature." (PMID 31866764, 2019). "Consistent with previous reports, we observed no EC-related deaths or evidence of recurrent tumors in both patients with POLE-mutant cancers." (PMID 31866764, 2019). "Potentially pathogenic variants were found in five Cancer Gene Census germline genes: GALNT12, POLE, MPL, ATM, and ERCC4." (PMID 30886832, 2019). "We also found that the prominent CD8+ T‐cell infiltrate present in POLE‐mutant cancers was evident in their precursor lesions." (PMID 29604063, 2018). "In POLE‐mutant cancers, the proportion of monoclonal predicted neoantigens was similar to that in other cancers, but the absolute number was much greater." (PMID 29604063, 2018). "In contrast, the differences in CD8+ density between EINs and paired carcinomas among both POLE‐wild‐type and POLE‐mutant cases were less marked (median 14.8 versus 24.7, p = 0.34, and 59.4 versus 116.9, p = 0.11, respectively)." (PMID 29604063, 2018). "Next-generation sequencing (NGS) (whole genome or exome) has facilitated further discovery of cancer susceptibility genes including RECQL, FANCM, FANCC, XRCC2, POT1, and BAP1 for breast and melanoma, and POLE, POLD1, and NTHL1 for CRC." (PMID 29212164, 2017). "Several lines of evidence indicate that germline and somatic POLE and PODL1 variants increase cancer predisposition by elevating mutation rates." (PMID 28117753, 2017).
cancer (continued). "Few alternation of A→G mutation frequency in cancers with only POLD1 or only POLE mutations can be explained by the strong function complementarity between POLD1 and POLE, reducing the influence of error-prone DNA polymerases." (PMID 28582771, 2017). "We combined these results with those from three additional series (n = 628) by meta-analysis to generate multivariable-adjusted, pooled hazard ratios (HRs) for recurrence-free survival (RFS) and cancer-specific survival (CSS) of POLE-mutant ECs." (PMID 25505230, 2015). "We recently showed that germline variants in the exonuclease domain of the DNA polymerases POLE and POLD1 predispose to cancer, including EC, by impairing polymerase proofreading and greatly increasing the rate of base substitution mutations." (PMID 25505230, 2015). "POLE proofreading-mutant cancers are a molecularly distinct group of tumors with a striking mutation burden and distinctive mutation signature." (PMID 25505230, 2015). "A set of cancers with a very large number of coding mutations (over 50 per 106 bases), in the absence of MMR defects or microsatellite instability (MSI), was also identified, and this set of cancers overlapped with the POLE-mutant set." (PMID 23447401, 2013). "Evidently, the identification of germline and somatic POLE and POLD1 mutations that cause CRC and EC is only the first stage in understanding how those changes act and, if possible, exploiting them for cancer prevention and therapy." (PMID 23447401, 2013). "The somatic mutation spectrum of POLE and POLD1 in the common cancers will be increasingly well described in the coming months as further large-scale sequencing programmes come to fruition." (PMID 23447401, 2013). "In a study performed by the TCGA, 17 cancers classified as ultramutated had a POLE EDM, including the most frequent P286R (exon 9) and V411L (exon 13) substitutions (eight and five cases, respectively) and one case each of M444K, A456P, L424I, and S297F substitutions." (PMID 40936703, 2025). "POLE mutations associated with cancer susceptibility and hypermutation do not cause complete LoF; instead, they result in the selective loss of exonuclease (proofreading) activity while retaining polymerase function." (PMID 40570257, 2025). "In addition, several miRNAs, such as hsa-miR-20b-5p, exhibited divergent expression patterns when comparing cancer versus healthy tissue and POLE+ versus POLE− tumors." (PMID 41226475, 2025). "Although POLD1 and POLE have recently been suggested as genes predisposing to hereditary EC, absolute risk for EC and even other cancer types is very uncertain, therefore the POLD1/POLE genetic testing of unselected EC patients should be restricted to the research setting." (PMID 40936703, 2025). "Overall, these results strongly indicate that POLE deficiency plays a critical role in DEE‐OEs‐induced malignant transformation, providing important insights into the mechanisms underlying DEE‐related cancer." (PMID 40583191, 2025). "Given the involvement of POLE mutants in most tumors, further exploration is warranted to determine whether POLE mutations also activate the cGAS-STING pathway in other cancer models." (PMID 38238314, 2024). "In summary, our findings highlight the potential of POLE mutation as a predictive biomarker for immune checkpoint blockade therapy and suggest targeted inhibition of POLE exonuclease activity as a promising approach to enhance the efficacy of anti-PD-1/PD-L1 treatment in cancers with WT POLE." (PMID 38238314, 2024). "Among hypermutated cancers presenting ≥10 Mut/Mb, ∼25% are associated with mutations in MMR genes alone, whereas a large number of ultra-hypermutated cancers (≥100 Mut/Mb) show mutations affecting both MMR and the replicative DNA polymerases, mainly POLE." (PMID 37891003, 2024).
cancer (continued). "Moreover, the French Genetic and Cancer Group-Unicancer recommended including not only POLE but also POLD1 in multi-gene panel genetic tests to evaluate the predisposition to hereditary cancer of the digestive tract." (PMID 39001389, 2024). "This suggests that the mechanism of mutation acquisition is similar throughout the cancer history irrespective of the POLE/POLD1 mutation." (PMID 39233831, 2024). "This potential sensitivity underscores the promise of small molecule inhibitors selectively targeting POLE exonuclease activity, which could significantly enhance the therapeutic efficiency of anti-PD-1/PD-L1 treatment in carcinomas with WT POLE." (PMID 38238314, 2024). "Here we present specific recommendations to apply the ACMG/AMP guidelines for the classification of variants located in the ED of POLE and POLD1, -where the variants associated with cancer predisposition are found-, and the scientific rationale applied for their definition." (PMID 37848928, 2023). "POLE mutation may lead to additional mutations, which can increase TMB and is a source of cancer hypermutation." (PMID 37986009, 2023). "POLE and POLD1 encode the catalytic subunit of the two main replicative polymerases in eukaryotes: polymerase epsilon and polymerase delta, respectively, and cancer-associated mutations affect their proofreading or intrinsic DNA repair activity." (PMID 36856825, 2023). "Unlike in POLE, where the overwhelming majority of cancer mutations are located in the exonuclease domain, POLD1 mutations occur in the exonuclease and polymerase domains, which is the location of the most recurrent POLD1 mutation, R689W." (PMID 37388540, 2023). "First phase: The test correctly identified 19 of 20 POLE-mutated carcinomas and showed a negative result in 60 cases that were previously known to lack a POLE mutation." (PMID 37874375, 2023). "The clinical strategies for reduction of molecular testing further encompass ESGO low-risk cases (e.g., with low grading and no LVSI) and should encounter the existence of multiple classifier carcinomas with combinations of POLE, MMRdef, and p53abn in up to 3% of cases." (PMID 37035329, 2023). "Although there are increasing numbers of reported cases of cancer patients with PolE mutations showing good response to immune checkpoint blockade of PD-1, some patients with PolE mutations still do not respond to the treatment." (PMID 35326618, 2022). "POLE missense variants are associated with the polymerase proofreading-associated polyposis (PPAP), a known autosomal dominant hereditary disease associated with the development of polyps and an increased risk of cancer at different sites." (PMID 35260767, 2022). "WGS data from the Pan-Cancer Analysis of Whole Genomes (PCAWG) dataset of 2,658 whole-cancer genomes across 38 tumour types found the most mutated DNA break repair mechanisms (DBRMs) genes to be FANCA, POLE, PRKDC and RAD51B." (PMID 36289474, 2022). "In addition to neoantigen load, another possible mechanism of the favorable outcome of PolE-mutant cancer patients is the “error threshold” theory." (PMID 35326618, 2022). "Carriers of POLE and POLD1 exonuclease domain germline mutations exhibited elevated somatic mutation burdens without evident cellular or organismal consequences, other than an increased cancer risk." (PMID 35803914, 2022). "Collectively, these results indicate that missense POLE mutations are not HCC-specific or cancer agnostic prognostic biomarkers." (PMID 35274726, 2022). "BRAF mutant cancers were more commonly MSI high or POLE positive." (PMID 36079062, 2022). "We leveraged multiple large genomic datasets to show that missense POLE mutations outside of the exo-domain are detected in a non-trivial proportion of cancers and are not HCC or cancer-agnostic prognostic markers." (PMID 35274726, 2022).
cancer (continued). "Moreover, Cox regression analysis elucidated a correlation between POLE expression and OS in pan-cancer, proving the universality of the influence of POLE expression on cancers." (PMID 34950188, 2021). "Moreover, in >12,000 pan-cancer samples, we found that POLE expression significantly predicted an immune-suppressive microenvironment because of the markedly negative correlation with abundance of many types of infiltrating immune cells." (PMID 34950188, 2021). "Except for increased cancer risk, individuals with germline POLE/POLD1 mutations do not exhibit overt features of premature aging." (PMID 34594041, 2021). "Next, we compared POLE expression levels between pan-cancer and normal tissues based on TCGA data." (PMID 34950188, 2021). "POLE-driven cases possess an abundance of TCT > TAT and TCG > TTG somatic mutations characterized by mutational signature 10 from the Catalog of Somatic Mutations in Cancer (COSMIC)." (PMID 34158040, 2021). "However, a significant association between the mutation status of POLE and high TMB was observed in 22 cancer types." (PMID 34198473, 2021). "When adjusting for cancer types and MSI status for multivariate Cox regression analysis, POLE/POLD1 mutations were found to be independent risk factors for identifying patients that could benefit from ICI treatment." (PMID 34026601, 2021). "Therefore, to explore the prognostic implications of POLE mRNA expression in cancers, we performed Cox regression analysis to identify the effect of POLE expression on the progression-free survival and OS of pan-cancer." (PMID 34950188, 2021). "Dasatinib, an identified anti-cancer drug was response against NSCLC cell lines with low POLE expression which could be treatment options for improving the survival of patients with NSCLC." (PMID 32433714, 2020). "An association between RAD54L germline mutation and POLE exonuclease domain hypermutated cancer has not been reported before." (PMID 32758138, 2020). "In addition, the frequency of MSI cases in POLE mutant tumors differed between the 3 cancer types (p < 0.001)." (PMID 32838755, 2020). "However, it is still feasible to screen multiple cancer related genes in EC patients from Middle Eastern region using multigene panels including POLE and POLD1." (PMID 31866764, 2019). "Hypermutation in cancer is associated with defective MMR and/or POLE functions." (PMID 31480372, 2019). "Since genes distal to the breakpoint were found to be unlikely to affect replication or repair, and loss of one copy of POLE does not predispose to cancer, selected experiments were possible on these cell lines." (PMID 31742432, 2019). "Since next generation sequencing technology offers significant benefits compared to single gene testing by reducing costs, time and increasing the sensitivity, it is feasible to screen multiple cancer related genes in EC patients using multigene panels including POLE and POLD1." (PMID 31866764, 2019). "This analysis showed that POLE mutations were unlikely to occur as late events after the most recent common ancestor in cancer evolution." (PMID 29604063, 2018). "There is therefore an indication that variants in POLE and POLE2 might be associated with susceptibility to multiple cancer types." (PMID 29641532, 2018). "Other cancer-related genes including TSG were also enriched in the POLE-dependent period." (PMID 29880869, 2018). "POLE somatic mutations in these cancers were recurrent in seven amino acids (p.P286R/H/L, p.S297F/Y, p.V411L, p.P436R, p.M444K, p.A456P and p.S459F), but the POLE p.E491K mutation in our result has not been reported." (PMID 28179590, 2017). "Using targeted capture sequencing of 504 cancer-related genes, we further validated whether these six MSS EOCRCs with a POLE P286R mutation were hypermutated." (PMID 27612425, 2016). "Based on this finding, we hypothesized that the early acquisition of POLE P286R may lead to somatic hypermutation, which in turn accelerates cancer development." (PMID 27612425, 2016).
cancer (continued). "However, of 109 grade 3 tumors, 0 of 15 POLE-mutant ECs recurred, compared with 29 of 94 (30.9%) POLE wild-type cancers; reflected in statistically significantly greater RFS (multivariable-adjusted HR = 0.11, 95% CI = 0.001 to 0.84, P = .03)." (PMID 25505230, 2015). "PPAP is a fairly recently described cancer susceptibility syndrome and guidelines regarding management of POLE and POLD1 mutation carriers do not yet exist." (PMID 25860647, 2015). "POLE/POLD1-mutated cancers displayed high SBS rates, ranging from 227 to 14,695 exonic events, compared to a range of 22 to 2,014 in cancers lacking POLE/POLD1 mutations." (PMID 24705290, 2014). "Consequently, POLe has been classified as a cancer driver gene." (PMID 40806338, 2025). "Notably, others have characterized an induced dependence on POLE in CCNE/CDK2 activated cancers, thus indicating that CIC::DUX4 may operate through a similar molecular pathway." (PMID 40760094, 2025). "PD-1 immunotherapy can achieved desirable response in cancer patients with sensitive gene mutations, including COL3A1, FGFR, breast cancer susceptibility (BRCA), ataxia telangiectasia-mutated gene (ATM), polymerase epsilon (POLE), DNA polymerase delta 1 (POLD1), NOTCH, KMT2C genes and so on." (PMID 39530091, 2024). "This treatment regimen was tailored based on comprehensive genomic profiling, which identified mutations in the POLE (catalytic subunit of DNA polymerase epsilon) and ATM (ataxia-telangiectasia mutated) genes, both of which have been implicated in the pathogenesis of various malignant tumors." (PMID 38933440, 2024). "Nonetheless, the reliable identification of cancer-driving POLE mutations in a cost-effective manner remains a significant challenge, although several POLE assays not based on NGS have been described that should be capable of reliably identifying POLE mutations." (PMID 38539494, 2024). "Considering the difference between driver mutations that push a cell toward a cancerous state and passenger mutations that are not directly responsible for the cancer phenotype of the cell, it is critical to characterize the pathogenicity of newly identified POLE EDMs." (PMID 36313640, 2022). "Moreover, the mutation rate in the PolE P286R mutant mouse cell line is estimated to be ~110 exon mutations per cell division, still not beyond the threshold of cancer cell survival." (PMID 35326618, 2022). "Our results also suggest that non-exo-domain POLE mutations may indicate benefit from ICIs in additional cancer types independent of TMB, but this requires prospective validation in larger studies." (PMID 35274726, 2022). "As POLE mutant cancers are usually hypermutated and individual mutants might lead to distinct mutator phenotypes, the precise mechanisms of mutagenesis may be revealed by investigating whether they show disparity in mutational spectrum and distribution across genomic regions." (PMID 32012149, 2020). "In addition, POLE ultra-mutant cancers also possess a high frequency of C-to-A transversions." (PMID 32838755, 2020). "However, recent analyses found frequent incidence of non-EXO POLE mutations in non-hyper-mutated cancers and a potential POLE contribution to the etiology of these cancers, arguing for the importance of non-EXO POLE variants in tumorigenesis." (PMID 32415104, 2020).